ERV3-1 (endogenous retrovirus group 3 member 1, envelope)
Description:
Retroviral envelope proteins mediate receptor recognition and membrane fusion during early infection. Endogenous envelope proteins may have kept, lost or modified their original function during evolution. This endogenous envelope protein has lost its fusogenic properties. It can inhibit cell growth through decrease expression of cyclin B1 and increased expression of p21 in vitro. SU mediates receptor recognition. TM anchors the envelope heterodimer to the viral membrane through one transmembrane domain. The other hydrophobic domain, called fusion peptide, mediates fusion of the viral membrane with the target cell membrane (By similarity).
Synonyms: ERV3; H-PLK; HERV-R; ERV-R; envR; ERVR; HERVR
Tractability: Antibody: UniProt predicts a signal peptide or a membrane-spanning region.
Gene: Protein-coding gene on chromosome 7 (64,990,356 to 65,006,743, reverse strand). Ensembl gene ENSG00000213462.
Subcellular location: Virion
Subcellular location (Human Protein Atlas): Vesicles; Cytosol; Golgi apparatus
Homologues: Paralogues in human: ERVV-2 (11% identical), ERVV-1 (11% identical), ERVMER34-1 (9% identical), ERVW-1 (9% identical), ERVFRD-1 (8% identical).
Diseases named in the same sentence as ERV3-1 in open-access papers:
ERV3-1 is named in the same sentence as 39 diseases in open-access papers, as found by Europe PMC text mining. Sharing a sentence is not in itself a finding about the gene and the disease. The quoted sentences say what the papers report.
Hodgkins lymphoma (5 papers, 2017 to 2023). A heterogeneous group of malignant lymphoid neoplasms of B-cell origin characterized histologically by the presence of Hodgkin and Reed-Sternberg (HRS) cells in the vast majority of cases. "Furthermore, the biological value of ERV3-1 has also been seen in its possible tumor-suppressing capabilities in Hodgkin’s lymphoma patients and upregulation in prostate cancer patients." (PMID 34944967, 2021).
breast carcinoma (3 papers, 2014 to 2021). "In conclusion, various HERV genes including HERV-R (ERV3-1), HERV-H, and HERV-P env show the same pattern of regulation as HERV-K (HML-2) and may be potent diagnostic markers and therapeutic targets for breast cancer patients." (PMID 24964007, 2014).
endometrial cancer (3 papers, 2021 to 2023). Primary or metastatic malignant neoplasm involving the endometrium (mucous membrane that lines the endometrial cavity). "Of interest is that during endometrial carcinoma progression, ERV3-1 ENV is co-expressed with six other ENV (HERV-W1, HERV-T, HERV-Fc2, HERV-H1-3, HERV-V1, HERV-E1) and showed significantly increased expression in more undifferentiated grade 3 tumors compared to differentiated grade 1 tumors." (PMID 34026614, 2021).
leukemia (3 papers, 2013 to 2023). A malignant (clonal) hematologic disorder, involving hematopoietic stem cells and characterized by the presence of primitive or atypical myeloid or lymphoid cells in the bone marrow and the blood. "In choriocarcinoma cells, ERV3-1 overexpression inhibits cell proliferation, while ERV3-1 is upregulated during terminal differentiation of leukemia cells and is highest in cell cycle arrested cells." (PMID 36979914, 2023).
prostate carcinoma (3 papers, 2017 to 2022). A carcinoma that arises from epithelial cells of the prostate gland. "Analogous results—significant induction of ERV3-1 and HERV-K but not HERV-E or HERV-W—were observed in the C4-2B model, demonstrating that this response occurs in both androgen-dependent (LNCaP) and androgen-independent (C4-2B) models of prostate cancer." (PMID 36923279, 2022).
lung adenocarcinoma (2 papers, 2014 to 2015). A carcinoma that arises from the lung and is characterized by the presence of malignant glandular epithelial cells. "HERV-R (ERV3-1) was highly expressed in normal organs and was significantly increased in various tumors, including lung adenocarcinoma, renal cell carcinoma, papillary carcinoma, hepatocellular carcinoma, and adenocarcinoma in the gastrointestinal tract." (PMID 24964007, 2014).
lymphoma (2 papers, 2021 to 2023). A malignant (clonal) proliferation of B- lymphocytes or T- lymphocytes which involves the lymph nodes, bone marrow and/or extranodal sites. "On the contrary, HERV-R.3-1 (HGCN: ERV3-1) has been proposed as tumor suppressor since its overexpression induced differentiation of the human BeWo choriocarcinoma cell line (see also HERVs in Lymphoma—The Silent Inducers)." (PMID 36979914, 2023).
psoriasis (2 papers, 2013 to 2021). An autoimmune condition characterized by red, well-delineated plaques with silvery scales that are usually on the extensor surfaces and scalp. "The biology of the other top DEGs according to their FDR value (ERV3-1, LSMEM1 and UBALD2) has not been extensively investigated and, to our knowledge, no specific relationships to CVD and psoriasis have been reported." (PMID 34639156, 2021).
acute myeloid leukemia (1 paper, 2021). Acute myeloid leukemia (AML) is a group of neoplasms arising from precursor cells committed to the myeloid cell-line differentiation. "High expression levels of the Env protein of ERV-3-1 were found in all patients with Acute myeloid leukemia (AML) included in one cohort while this effect was more specific for bone marrow and blood cells and was closely associated with a myeloid phenotype of AML in this study." (PMID 34778024, 2021).
colorectal cancer (1 paper, 2021). A primary or metastatic malignant neoplasm that affects the colon or rectum. "The overexpression of ERV3-1 is associated with several tumor entities like prostate, lung, liver and colorectal cancer." (PMID 33996550, 2021).
metastatic tumors (1 paper, 2023). "Genes such as SZRD1 and ERV3-1 were upregulated in the metastatic tumors of ST survivors, as previously reported in other solid cancer types such as cervical and colorectal cancer." (PMID 37400526, 2023).
Obesity (1 paper, 2023). Accumulation of substantial excess body fat. "Additionally, investigation of linkage disequilibrium around rs67047829 and -omics studies comparing subjects with each genotype might elucidate a role for the ERV3-1/ZNF117 locus in obesity." (PMID 37816715, 2023).
systemic lupus erythematosus (1 paper, 2023). An autoimmune multi-organ disease typically associated with vasculopathy and autoantibody production. "In early studies, sera from pregnant women, as well as those from patients with Sjögren syndrome or systemic lupus erythematosus (SLE), exhibited increased antibody reactivity against a peptide corresponding to a predicted epitope from the ERV3–1 envelope glycoprotein and to recombinant protein." (PMID 36630597, 2023).
type-2 diabetes (1 paper, 2023). "rs67047829 forms a pretermination codon in ERV3-1 and potentially lies in a regulatory region of ZNF117, which has various intriguing connections with ERV3-1 and is already known to have association with cellular adipogenesis and type-2 diabetes." (PMID 37816715, 2023). "rs67047829 gives a pretermination codon in ERV3-1 which shares an exonic region and possibly promoter with ZNF117, previously associated with adiposity and type-2 diabetes." (PMID 37816715, 2023).
tumor (17 papers, 2005 to 2025). "Thus, our spatial transcriptome analysis revealed that RT induces the formation of immunologically hot sites in regions of ESCC tumours containing cancer cells, in which the ERV3-1, DDX58, and virus response pathways are upregulated." (PMID 37543704, 2023). "In addition, we investigated their potential to reverse the downregulation of MHC-I, ICAM-1, and B7-2 in these tumor cells and the potential role of drug-induced changes in gammaherpesvirus and ERV3-1 expression on these effects." (PMID 35562811, 2022). "The role of ERV3-1 in cancer appears to be different in several tumor entities." (PMID 33996550, 2021). "We previously analyzed the HERV-R (ERV3-1) env protein in both adult human organs and in tumors using a tissue microarray and also compared the expression of HERV-R (ERV3-1) between normal and tumor tissues to study the relationship between HERV-R (ERV3-1) and tumor formation." (PMID 24964007, 2014). "Finally, ERV3‐1 did not clearly appear as a tumor‐specific transcript since most of the cohorts displayed similar expression in normal tissues, control, and tumor samples, with sporadic activation or inactivation of the sequence." (PMID 34318590, 2022).
cancer (10 papers, 2012 to 2024). A tumor composed of atypical neoplastic, often pleomorphic cells that invade other tissues. "These DNAm sites were mapped to genes that play mechanistic roles in multiple cancers, such as cg06513015 on ERV3-1, cg09516963 on DYRK2, cg26919182 on PPP1R12B, and cg17612569 on GABPA and ATP5J." (PMID 36966332, 2023).
infection (2 papers, 2022 to 2023). The state of being infected such as from the introduction of a foreign agent such as serum, vaccine, antigenic substance or organism. "ERV3-1 is an evolutionary remnant from a human endogenous retrovirus (HERV) infection, and protein truncation might still have possible biological consequences." (PMID 37816715, 2023).
inflammation (1 paper, 2021). Aberrant reaction of the microcirculation characterized by movement of fluid and leukocytes from the blood into extravascular tissues. "CEACAM1 correlated with vascular inflammation in the aorta, and CEACAM1, MMP9, MPO, ERV3-1, UBALD2 and LSMEM1 correlated with vascular inflammation in the carotid arteries." (PMID 34639156, 2021).
ERV3-1 also shares sentences with these, for which no sentence is quoted: ovarian cancer (10 papers); choriocarcinoma (4); adenocarcinoma (1); cervical cancer (1); colon cancer (1); colorectal (1); congenital heart block (1); endometrial polyp (1); hepatocellular carcinoma (1); hyperplasia (1); lung carcinoma (1); melanoma (1); myelocytic leukemia (1); neurodegenerative disease (1); papillary carcinoma (1); preeclampsia (1); pregnancy disorder (1); prostate tumor (1); renal cell carcinoma (1); testis tumor (1); Wilms tumor (1).